RNA5SP533 (RNA, 5S ribosomal pseudogene 533)
Gene: Ribosomal RNA gene on chromosome 1 (143,439,605 to 143,439,714, forward strand). Ensembl gene ENSG00000252830.
Homologues: Orthologues: chimpanzee 5S_rRNA (100% identical). Paralogues in human: 5S_rRNA (100% identical), RNA5SP529 (100% identical), RNA5SP536 (71% identical), RNA5SP443 (70% identical), RNA5S1 (68% identical), RNA5S10 (68% identical), RNA5S11 (68% identical), RNA5S12 (68% identical), RNA5S13 (68% identical), RNA5S14 (68% identical), RNA5S15 (68% identical), RNA5S16 (68% identical), and 26 more.